TFIP11 (tuftelin interacting protein 11)
Description:
Involved in pre-mRNA splicing, specifically in spliceosome disassembly during late-stage splicing events. Intron turnover seems to proceed through reactions in two lariat-intron associated complexes termed Intron Large (IL) and Intron Small (IS). In cooperation with DHX15 seems to mediate the transition of the U2, U5 and U6 snRNP-containing IL complex to the snRNP-free IS complex leading to efficient debranching and turnover of excised introns. May play a role in the differentiation of ameloblasts and odontoblasts or in the forming of the enamel extracellular matrix.
Synonyms: STIP-1; STIP; TIP39; DKFZP434B194; Spp382; NTR1; bK445C9.6
Tractability: Small molecule: a structure with a bound ligand is known. Antibody: its Gene Ontology location is reachable by antibodies, with medium confidence. PROTAC: ubiquitination databases record sites on it; its protein half-life has been measured.
Gene: Protein-coding gene on chromosome 22 (26,490,988 to 26,512,505, reverse strand). Ensembl gene ENSG00000100109.
Subcellular location: Cytoplasm; Nucleus
Subcellular location (Human Protein Atlas): Nucleoplasm; Cytosol
Pathways (Reactome):
Metabolism of RNA: mRNA Splicing - Major Pathway
Gene Ontology:
Molecular function: protein binding; nucleic acid binding
Biological process: negative regulation of protein-containing complex assembly; spliceosomal complex disassembly; mRNA splicing, via spliceosome; negative regulation of double-strand break repair via nonhomologous end joining; protection from non-homologous end joining at telomere; RNA processing
Cellular component: catalytic step 2 spliceosome; chromosome, telomeric region; nuclear speck; nucleolus; spliceosomal complex; U2-type post-mRNA release spliceosomal complex; nucleoplasm; cytoplasm; extracellular matrix; nucleus
Genetic constraint (gnomAD): Loss-of-function variants: 86 observed, 100.99 expected, observed/expected ratio (o/e) 0.85, 90% interval 0.71 to 1.02. The upper end of that interval is the gene's LOEUF score, 1.02, which puts it in group 4 of 6, group 1 being the genes least tolerant of losing a copy. Missense variants: 881 observed, 1,123.2 expected, observed/expected ratio (o/e) 0.78, 90% interval 0.74 to 0.83. Synonymous variants: 405 observed, 415.95 expected, observed/expected ratio (o/e) 0.97, 90% interval 0.9 to 1.06.
Homologues: Orthologues: chimpanzee TFIP11 (99% identical), macaque TFIP11 (99% identical), pig TFIP11 (98% identical), dog TFIP11 (97% identical), guinea pig TFIP11 (97% identical), rabbit TFIP11 (95% identical), rat Tfip11 (92% identical), mouse Tfip11 (92% identical), tropical clawed frog tfip11 (80% identical), zebrafish tfip11 (66% identical), Drosophila melanogaster sip1 (37% identical), Caenorhabditis elegans stip-1 (31% identical). Paralogues in human: ZGPAT (10% identical), LIME1 (4% identical).
Diseases named in the same sentence as TFIP11 in open-access papers:
TFIP11 is named in the same sentence as 5 diseases in open-access papers, as found by Europe PMC text mining. Sharing a sentence is not in itself a finding about the gene and the disease. The quoted sentences say what the papers report.
dental caries (3 papers, 2017 to 2023). The decay of a tooth, in which it becomes softened, discolored, and/or porous. "Genetic association studies of dental caries have suggested that caries may be influenced by variations in enamel formation genes, such as ameloblastin (AMBN), amelogenin (AMELX), enamelin (ENAM), matrix metalloproteinase 20 (MMP20), tuftelin (TUFT1), and tuftelin-interacting protein 11 (TFIP11)." (PMID 29163197, 2017). "In this case–control study, 15 SNPs in ALOX15, AMBN, AMELX, KLK4, TFIP11, and TUFT1 genes were analyzed in 150 children with primary dentition and 611 children with permanent teeth with/without dental caries from the European Longitudinal Study of Pregnancy and Childhood (ELSPAC) cohort." (PMID 36422720, 2023).
TFIP11 also shares sentences with these, for which no sentence is quoted: dental fluorosis (2 papers); asthma (1); cancer (1); non-small cell lung carcinoma (1).